TLR7 (toll like receptor 7)
Diseases named in the same sentence as TLR7 in open-access papers (continued):
Sharing a sentence is not in itself a finding about the gene and the disease.
lung carcinoma (continued). "The discovery that innate immune receptors (i.e., FPR1 in gastric cancer and TLR7 in lung cancer) might control PUFA metabolism, inflammation resolution, angiogenesis, and cancer opens new possibilities to be exploited for cancer treatment." (PMID 33578955, 2021). "Altogether, these data support the hypothesis that TLR7 could be the PRR responsible for the maintenance of the pro-resolving tone in lung cancer epithelial cells." (PMID 33578955, 2021). "We hypothesized that TLR7 is the main sensor of damages and modulator of the balance between inflammatory and pro-resolving responses in the context of lung cancer." (PMID 33578955, 2021). "We identified TLR7 as an inhibitor of lung cancer vascularization." (PMID 33578955, 2021). "In the context of lung cancer, Fabbri and colleagues reported on a systematic approach using NanoString technology, thereby identifying miRNAs present in exosomes from immortalized lung cancer cells as activators of TLR7/8." (PMID 31940779, 2020). "For example exosomes derived from lung cancer cells transferred miR‐21/29a to activate TLR7 and TLR8 on immune cells, which may contribute to tumour growth and metastasis." (PMID 32391938, 2020). "In lung cancer, activation of TLR7 and TLR8increases survival and chemoresistance of the tumor cells;therefore these two TLRs could be targets for tumorimmunotherapy." (PMID 30237679, 2018). "Furthermore, different types of CpG ODN like DV281 (Class C) and TLR7/8 agonists are being used in combination with immune checkpoint inhibitors like an anti-PD-1 antibody to induce immune cytokine and chemokine responses during lung cancer immunotherapy." (PMID 36389785, 2022). "In the light of our observation of the therapeutic potential of Loxoribin in colon cancer and lung cancer, TLR7 therapy may be important for human cancer, and TLR7 ligands and their analogs could be immunotherapeutic modalities in cancer patients in the future." (PMID 25593198, 2015). "TLRs have been shown to be overexpressed in different cancers, such as TLR7 and TLR8 in pancreatic cancer; TLR3, TLR4, TLR7, and TLR9 in esophageal cancer; TLR4, TLR5, and TLR7–9 in lung cancer; and TLR2–5 in ovarian cancer." (PMID 36890302, 2023). "Similar with the bioinformatics results in TCGA database, our experiments confirmed the expression of CLEC7A, TLR7, IL-1A and IL33 were decreased in lung cancer." (PMID 37259066, 2023). "ZEB1, TRAF4, and TGF-β1 are involved in lung cancer metastasis by EMT proteins while PD-L1, EGFR, TLR7 and TLR8 are involved in inhibiting the immune system." (PMID 36032679, 2022). "Both TLR7 and TLR8 stimulation activate the NF-κB pathway, thought to improve cell survival, inflammation, and chemoresistance in primary lung cancer cells." (PMID 36389785, 2022). "MiR-574-5p derived from small extracellular vesicles activated TLR7/8, thereby decreased PGE2-levels in lung cancer." (PMID 35413927, 2022). "EV-miR-21 and miR-29a from lung cancer cells induce NF-κB activation and the release of prometastatic inflammatory cytokines in murine and human macrophages by activating TLR7 and TLR8 respectively, which promotes lung cancer metastasis." (PMID 32503543, 2020). "Triggering of TLR7 and TLR8 expressed by human lung cancer cells induced cell survival and chemo-resistance." (PMID 29568370, 2018). "We incubated HEK-Blue cells expressing human TLR2, TLR3, TLR4, TLR5, TLR7, TLR8, TLR9, or the intracellular PRR protein NOD2 with 100 μg/ml DRibbles derived from the mycoplasma free lung cancer cell line UbiLT3." (PMID 27490927, 2016). "In lung cancer, TLR5 was correlated with good prognosis, but TLR7 with poor prognosis." (PMID 32174922, 2020).
lupus nephritis (40 papers, 2012 to 2026). Glomerulonephritis in the context of systemic lupus erythematosus. "TLR-7 is implicated in the pathogenesis of lupus nephritis in both murine and human studies by recognizing endogenous ribonucleoprotein antigens, thus activating antigen-presenting cells." (PMID 39337618, 2024). "CD43 expression is the hallmark of CD11b+ patrolling monocytes (PMo) that drives TLR7-induced lupus nephritis." (PMID 35860280, 2022). "Treml4−/− MRL/lpr mice have lower autoantibody and interferon-α production and improved survival vs. Treml4+/+ controls, suggesting that Treml4 plays a causal role in lupus nephritis by upregulating TLR7-driven interferon production." (PMID 36264674, 2022). "B cell–specific TLR7 drives severe lupus nephritis in TLR9-deficient MRL/lpr mice." (PMID 37606042, 2023). "TLR7 SNP rs3853839 has also been linked to lupus nephritis, according to." (PMID 36439744, 2022). "Here, we investigated the pathogenic role of TLR7 in NZBWF1 mice using an anti-TLR7 inhibitory mAb This mAb ameliorated lupus nephritis in NZBWF1 mice by acting on B cells and monocytes/macrophages, thereby reducing IgG deposition in glomeruli and diminishing autoantibody production." (PMID 34868046, 2021). "Polymorphisms in HLA class II, TLR7 and FBN2 are notably linked to serious consequences, including lupus nephritis (LN)." (PMID 42123548, 2026). "Beyond its role in B cells, TLR7 is also critical within the renal tissue of patients with lupus nephritis (LN), where single strand RNA (ssRNA) drives aberrant TLR7 activation in macrophages." (PMID 41869359, 2026). "Our study demonstrates that VEGFR-3 inhibition reduces TLR7/MyD88/IFN-α signaling in lupus nephritis." (PMID 40651955, 2025). "Separately, TLR7 agonism has been shown to accelerate SLE101 while TLR7 neutralisation protects against lupus nephritis." (PMID 39586195, 2024). "In lupus nephritis, TLR7/9 signaling within the kidney microenvironment downregulates integrin α4β7 expression, leading to decreased Areg production and promoting the egress of ILC2s." (PMID 38806623, 2024). "Deletion of TLR7 in B cells via a mixed BM chimera mildly suppresses lupus nephritis and improves B cell lymphopenia in female mice." (PMID 37606042, 2023). "A recent study showed that monotherapy with TAC significantly diminished proteinuria and Toll-like receptor-7 expression and induced the suppression of IL-6 production in lupus nephritis mice." (PMID 33865397, 2021). "As IL-10 promotes glomerular damage by increasing mesangial proliferation and the mesangial deposition of immune complexes, our results suggested that the TLR7-dependent production of IL-10 in glomerular patrolling monocytes promotes lupus nephritis." (PMID 34868046, 2021). "TLR7 activation with imiquimod activates systemic type I interferon production and aggravates lupus nephritis in MRL/lpr mice." (PMID 29650017, 2018). "Overall, TLR7, − 8, and 9 drive lupus nephritis because endogenous (and during infections possibly exogenous) nucleic acid-based TLR agonists activate infiltrating antigen-presenting cells inside the nephritic kidney." (PMID 29650017, 2018). "Male Tlr7−/−/Yaa mice develop less severe lupus nephritis than Tlr7+/Yaa B6.Nba2 congenic mice suggesting that increased copy number results in increased disease progression." (PMID 25229618, 2014). "In addition, the nucleic acid component of immune complexes activates intrarenal macrophages via TLR7, resulting in the activation of glomerular endothelium and mesangial cells in lupus nephritis." (PMID 38772735, 2024). "Activation of TLR-7 with imiquimod exacerbates lupus nephritis in MRL-lpr/lpr mice." (PMID 39337618, 2024). "Similarly to monocytes, TLR7 hyperactivity in mDCs was previously suggested to drive lupus nephritis in murine models." (PMID 36172362, 2022). "Moreover, TLR7 agonists were demonstrated to drive lupus nephritis in murine models and, conversely, TRL7 blockade protects from the disease." (PMID 36172362, 2022).
lupus nephritis (continued). "Based on a model developed for TLR-induced lupus nephritis, we propose that acute TLR7 activation activates intravascular PMos and triggers the endothelium to express increasing amounts of adhesion molecules and chemokines, which promote prolonged contact with PMos." (PMID 35860280, 2022). "Blockades of TLR7/9 ameliorate lupus nephritis development, which may be partially due to the depletion of autoreactive B cells." (PMID 31795353, 2019). "Thus, TLR7-mediated RNA sensing in conventional dendritic cells is an essential component in lupus nephritis in mice." (PMID 29650017, 2018). "Activation of TLR7 leads to transcription of type I interferons and the pro-inflammatory cytokines IL-6, IL-10 and TNFα through the NF-κB pathway, promoting inflammatory progression in lupus nephritis." (PMID 29190833, 2017). "Administration of TLR7 agonists (imiquimod and R848) can induce lupus nephritis with increased serum ANA levels, especially anti-dsDNA IgG levels, in which enhanced activation of autoreactive B cells might be responsible for the autoantibody production." (PMID 26068236, 2015). "Moreover, topical application of the TLR7 agonist imiquimod induces lupus nephritis in mice." (PMID 40910948, 2026). "Moreover, this anti-TLR7 mAb ameliorates lupus nephritis in NZBWF1 mice." (PMID 40910948, 2026). "However, little is known about the cellular mechanisms through which TLR7 drives lupus nephritis." (PMID 34868046, 2021). "As a result, we demonstrate that TLR7–9 as well as the Clec4e receptor and downstream signalling molecules are up-regulated in untreated lupus prone mice, and most importantly, while less pronounced, also in human lupus nephritis ISN/RPS class IV, even though these patients were under treatment." (PMID 22479529, 2012). "TLR3, TLR7, and TLR9 were reported in the kidneys of patients with lupus nephritis (LN) in correlation with the clinic-pathological indices." (PMID 39000140, 2024). "The purpose of this study was to compare the plasma expression of TLR7 and TLR9 in HC and in recently diagnosed Class III and Class IV lupus nephritis (LN) patients with 12-month follow-up." (PMID 39000140, 2024). "Thus, expression of TLR7 in tubular cells, in addition to professional antigen presenting cells, may contribute to local interferon levels and transcription of other proinflammatory cytokines, driving lupus nephritis progression." (PMID 29190833, 2017). "TLR7 membrane antibody blocked the negative TLR7 signaling and decreased the serum anti-DNA antibodies, thus alleviating lupus nephritis in NZB/WF1 mice." (PMID 39960645, 2025). "The results showed that both of the nanoflowers, as specific antagonists for TLR7 and TLR9, could decrease the level of autoantibodies, reduce cytokine secretion, and alleviate lupus nephritis in mice." (PMID 36555668, 2022). "IRS 954 simultaneously exerting TLR7/9 signaling showed weak down-regulation of dsDNA IgG2a, dsDNA IgG2b, and Smith antigen autoantibodies, but it was not helpful in lupus nephritis." (PMID 36555668, 2022). "In contrast, blockade of TLR7, TLR9, or both attenuates lupus nephritis." (PMID 34760904, 2021). "In the light of the promising data demonstrating the efficacy of a dual TLR7/TLR9 antagonist and suggesting an “anti-TLR7/9” effect of antimalarials, the results of this study further support the role of TLRs as potential target of lupus nephritis." (PMID 27635115, 2016). "The TLR7 blocker of the IRS 661 nanoflower and the TLR9 antagonist of the IRS 869 nanoflower could decrease autoantibodies, reduce cytokine secretion, and alleviate lupus nephritis in mice." (PMID 36555668, 2022). "However, CD16+ monocytes accumulated in the glomerulus of kidneys in lupus nephritis patients and the stimulation of TLR7 in non-classical monocytes led to inflammation that was related to the pathogenesis of lupus nephritis." (PMID 35371102, 2022).
lupus nephritis (continued). "Additionally, in nephritic lesions of MRLlpr/lpr mice, TLR7 is expressed on renal macrophages and contributes to the production of pro‐inflammatory mediators, including IL‐12, IL‐6, CCL2, and IFN‐α, which is known to contribute to the progression of lupus nephritis." (PMID 28665028, 2017). "However, the IRS 954 nanoflower, the TLR7 and TLR9 dual antagonist, did not have additive or opposing effects on lupus nephritis but only showed a decrease in serum IFNα, suggesting that the TLR7 and TLR9 antagonist may have a competition mechanism or signal-dependent switching relationship." (PMID 36555668, 2022). "In sum, the vector that point at chromatin-IgG deposits in GBM are clustered with vectors pointing at TLR7–9, Clec4e, MMP2 and MMP9, indicating an interdependency between them, while the DNaseI vector points the opposite direction due to its negative correlation with advanced lupus nephritis." (PMID 22479529, 2012).
breast carcinoma (38 papers, 2012 to 2026). "TLR2 signaling has been demonstrated to induce migration in human breast cancer cells) and ligation of TLR7 and -8 has been associated with proliferation and chemoresistance in pancreatic cancer (TLR7 and -8)." (PMID 27941651, 2016). "Several studies have explored the potential therapeutic applications of TLR7 agonists or antagonists in combination with other immunotherapeutic approaches for breast cancer treatment." (PMID 38903515, 2024). "In recent years, research has uncovered the potential significance of TLR7 in breast cancer, with evidence suggesting both pro-tumorigenic and anti-tumor effects." (PMID 38903515, 2024). "Overall, while TLR7 holds promise as a target for breast cancer therapy, further research is needed to fully understand its role in breast cancer progression and its potential as a therapeutic target." (PMID 38903515, 2024). "Subsequently, tumor digests of breast cancer samples with solid pDC infiltration and whole blood samples of healthy donors were stimulated with a TLR7 agonist (RO7117419) for 24 hrs." (PMID 39575246, 2024). "TLR7 activation by ssRNA or synthetic agonists has been shown to promote breast cancer cell proliferation, migration, and invasion in vitro." (PMID 38903515, 2024). "In conclusion, a novel vaccine for breast cancer was developed with three components: a small-molecule TLR7 agonist (SZU251), an MUC1-related peptide (MUC1) and an aluminum adjuvant (Al)." (PMID 36499455, 2022). "Intratumoral delivery of cytosine–phosphate–guanine oligodeoxynucleotides (CpG ODN), a TLR9 agonist, or of R848, a TLR7/8 agonist, showed tumoricidal activity in melanoma and breast cancer mouse models." (PMID 35163420, 2022). "The FOLRβ being upregulated in TAM, treatment of mice with orthotopic breast cancer with a folate-targeted TLR7 agonist showed a decrease of tumor mass and reprogramming of TME including TAM." (PMID 35163420, 2022). "Imiquimod is a well-tolerated TLR7 agonist that can promote the rejection of immune-mediated skin metastasis in breast cancer patients 852A is another TLR7 agonist used for the treatment of metastatic breast cancer patients." (PMID 33747948, 2021). "Treatment using TLR-7 agonist, imiquimod and systemic albumin bound paclitaxel for recurrent chest wall lesion in breast cancer is effective in inducing disease regressing with a response rate of 20–30%." (PMID 34680503, 2021). "STAT3 inhibition and TLR7/8 pathway stimulation in MDSCs repolarize and suppress MDSCs from breast cancer patients." (PMID 33679700, 2020). "TLR7 was identified as one of the PRRs-sensing exosomes that contribute to the stimulation of downstream pathways in breast cancer cells." (PMID 30736860, 2019). "In conclusion, to our knowledge, this is the first report on the antitumor effects of combination therapy using TKIs and a TLR7 agonist in breast cancer treatment." (PMID 28000738, 2016). "Immune analyses of these long-term disease-free breast cancer patients previously treated with imiquimod (IMQ) suggest in-situ vaccination is achieved by topical application of the TLR-7 agonist directly onto tumors." (PMID 28837000, 2014). "In a model of human HER-2/neu(+) breast cancer (neu-transgenic mice), topical treatment with a TLR7 agonist, imiquimod, showed significant regression of spontaneous breast cancers." (PMID 24904578, 2014). "Our immune evaluation of long-term disease-free breast cancer patients suggests in-situ vaccination is achieved by application of the TLR7- agonist directly onto tumors and subsequent endocrine therapy can expand these responses." (PMID 28837000, 2014). "This study aims to explore the individual effects of TLR7/8 agonists and to compare their cytotoxic properties with those of the chemotherapy drug doxorubicin on 4T1 breast cancer cells, as well as to evaluate their role in the modulation of immune checkpoint molecules." (PMID 41550509, 2026).